ALB (albumin)
Diseases named in the same sentence as ALB in open-access papers (continued):
Sharing a sentence is not in itself a finding about the gene and the disease.
colon carcinoma (continued). "In the left-sided colon tumour subgroup, all three score types were independent factors for OS (mGPS, p = 0.029; SIS p = 0.0013; albumin-NLR, p = 0.001)." (PMID 30419863, 2018). "C-reactive protein (CRP), albumin, IL-1α, IL-1β, IL-6, IL-8, IL-10, TNF-α, midkine, VEGF-A, VEGF-C, leptin, adiponectin, and ghrelin serum levels are studied in 126 colon cancer patients and 36 healthy subjects." (PMID 20920199, 2010). "The multivariable Cox regression analysis included variables that have been found to be associated with a higher NLR0 in the preliminary univariable analysis: sex, CRF, IHD, AF/PAF, colon cancer, smoking history, WBC, Hemoglobin, platelet count, MCV, RDW, Urea, Creatinine, and Albumin." (PMID 36675385, 2023). "The colon cancer induced by AOM leads to a severe oxidative injury that leads to lipid peroxidation in colon tissue and the blood cells, which consequently stimulates more protein (albumin) secretion by the kidneys, increasing the blood urea level." (PMID 36826002, 2023). "We explored the relationship between the platelet-lymphocyte ratio (PLR), the prognostic nutritional index (PNI), the lactate dehydrogenase-albumin ratio (LDH/albumin ratio; LAR), the controlling nutritional status (CONUT) score, and the long-term survival of colon cancer patients." (PMID 35295561, 2022). "Clinically investigated ruthenium complexes, KP1019 and its sodium salt analogue KP1339, which are active against colon carcinomas, were thought to exhibit tumor selectivity via HSA (Human Serum Albumin) mediated pathways based on increased permeability and the retention effect of tumor tissues." (PMID 33066568, 2020). "By comparing 55 SSI and propensity score matched- 55 non-SSI patients receiving elective radical resection of colon cancer, we discovered that patients with preoperative lower albumin level, higher RAT, AD, and RAT × AD values augments the risk of SSI." (PMID 31380276, 2019). "To the best of our knowledge, we are the first to report that the pretreatment combination of BMI and albumin levels along with CRP levels, which we defined as the NCR in the present study, is an independent indicator of a poor prognosis for patients with primary untreated colon cancer." (PMID 36611408, 2022). "The study indicated that the modified albumin NPs targeted the drug-resistant colon cancer cells (HCT8/ADR) and their microenvironment via multiple nutrient transporters, such as SPARC and mannose receptors, and displayed higher uptake efficiency than the non-modified albumin NPs." (PMID 35203695, 2022). "Dynamic contrast-enhanced (albumin-Gd-DTPA) magnetic resonance imaging, performed during 2 weeks of daily administration of an inhibitor of tyrosine kinase receptors (SU6668) in an HT-29 colon carcinoma model, revealed the onset of a hyper-enhancing rim, not observed in untreated tumours." (PMID 19384298, 2009).
hepatitis B (70 papers, 2011 to 2026). "Higher levels of plasma albumin mRNA were also detected in LC and active hepatitis B patients with a diagnostic sensitivity of more than 85% and specificity for detection over 90%." (PMID 32577166, 2020). "Upon repeated exposure to fialuridine, a discontinued anti-hepatitis B drug known for causing severe liver toxicity in humans, the tissue model exhibited barrier compromise, reduced albumin production, and increased levels of ALT and AST in a time- and concentration-dependent manner." (PMID 40575028, 2025). "Multivariable analysis revealed that albumin, hepatitis B and TACE-RFA were associated with PFS." (PMID 31640620, 2019). "Finally, the prominent weighting of albumin and γ‐GT in our Chinese cohort likely reflects the elevated local prevalence of hepatitis B virus infection and the associated alterations in liver reserve and cholestatic biochemistry that distinguish Asian from Western ICC populations." (PMID 41331584, 2025). "GAG–HCC score predicts the occurrence of HCC in patients with hepatitis B within 5 and 10 years based on age, gender, albumin, bilirubin, HBV DNA and LC." (PMID 38744926, 2024). "The independent prognostic indicators of OS included albumin (ALB), cancer embolus, blood loss, viral hepatitis B, total bilirubin (TB), microvascular invasion, overweight, and major resection." (PMID 38854717, 2024). "The following were collected: sociodemographic, anthropometric, and clinical data; venous blood samples for creatinine, hepatitis B serology; DNA extraction; spot urine samples for dipstick testing and urine albumin: creatinine ratio (UACR) measurement." (PMID 36457874, 2022). "The univariate Cox regression analysis of the risk score and clinical characteristics (including gender, age, TNM stage, tumor size, hepatitis B, Lymph node invasion, vascular invasion, perineural invasion, albumin, AFP, CEA, and CA199) was performed." (PMID 35720008, 2022). "Among Child-Pugh class A, serum albumin was more likely to decrease in hepatitis B, C-CLD (p=0.089), and serum creatinine was more deranged in the same group (p=0.101)." (PMID 33520498, 2020). "The groups differed significantly in terms of Hepatitis B and Hepatitis C status (p < 0.001) and mean serum albumin (p < 0.001)." (PMID 31039745, 2019). "Serum α-fetoprotein level and treatment method were important independent prognostic factors for OS, whereas albumin, hepatitis B and treatment method were important independent prognostic factors for PFS." (PMID 31640620, 2019). "This audit also demonstrated stock-outs of haemoglobin, blood glucose, syphilis, hepatitis B, and urine protein/albumin POC test kits in the majority of the rural clinics." (PMID 30811407, 2019). "The levels of albumin were significantly (P < 0.05) decreased in individuals with hepatitis B and C when compared with the control group." (PMID 29805400, 2018). "It is evident that from the 25th percentile score majority of hepatitis B patients have serum albumin ≥3.4 g/dl." (PMID 29506525, 2018). "Nevertheless, circulating mRNAs, especially albumin mRNA, showed much more sensitivity in distinguishing active hepatitis B, hepatitis B carrier or HCV patientsfrom healthy control." (PMID 24643113, 2014). "Significant differences were observed between the PDAP and control cohorts in sex, age, hospitalization time, PD duration, red blood cell count, total protein, albumin, blood glucose, and concomitant conditions (e.g., hepatitis B, autoimmune diseases, and hyperthyroidism) (p < 0.05)." (PMID 41017908, 2025). "In addition, serum albumin level appeared to be an indicator of immunogenicity after hepatitis B vaccination among dialysis patients." (PMID 33420114, 2021). "Compared to the nTx, the Tx group had a lower BMI, a higher number of patients with positive serology for viral hepatitis (3 with hepatitis B, 3 with hepatitis C and 1 with both), lower concentrations of potassium and albumin and higher levels of ferritin and transferrin saturation." (PMID 31978190, 2020).
hepatitis B (continued). "The key words used included ‘Hepatitis B’, ‘Vaccine’, ‘Dialysis’, ‘Hemodialysis’, and ‘Albumin’." (PMID 29201314, 2017). "These mice were shown to support the replication of human hepatitis B and C. The basis of this system is the use of a transgenic mouse expressing the gene urokinase plasminogen activator (uPA) under control of the strong liver specific albumin promoter in a highly immunodeficient mouse background." (PMID 24155939, 2013). "We measured aflatoxin B1 albumin (AF-ALB) adduct levels and vitamins A and E concentrations in the plasma of HIV-positive and HIV-negative Ghanaians and examined the association of vitamins A and E with HIV status, aflatoxin levels and hepatitis B virus (HBV) infection." (PMID 22078415, 2011). "Subsequently, a modified PAGE-B (mPAGE-B) model was constructed by adding serum albumin level to the PAGE-B model in 2001, treated Asian hepatitis B patients, and showed 0.82 of AUROC." (PMID 36902191, 2023). "Age, gender, Child-Pugh class, hepatitis B virus (HBV) infection ratio, alpha fetoprotein (AFP) levels, albumin-bilirubin (ALBI) score, BCLC stage and ECOG-PS score were examined." (PMID 34988019, 2021). "Patients in non-hepatitis B, C-CLD group had lower serum albumin levels, similar to that in hepatitis B, C-CLD group." (PMID 33520498, 2020). "Some variables differed between the groups, including ECOG, hepatitis B infection, ALBI score, and levels of albumin and alkaline phosphatase." (PMID 32850352, 2020). "Several other tests were reported in some studies including hepatitis B and C test, liver biopsy, complete blood count (CBC), serum albumin, alanine aminotransferase (ALT), aspartate aminotransferase (AST), and test for active S. mansoni infection." (PMID 32028581, 2020). "Our analysis identified ten variables associated with a higher risk of mortality: older age, disease duration exceeding 5 years, frequency of ascites exceeding 5 episodes, concurrent hepatitis B, and elevated baseline levels of ALT, AST, DBil, ALP, ALB, and AFP." (PMID 40424464, 2025).
acute coronary syndrome (68 papers, 2013 to 2026). Signs and symptoms related to acute ischemia of the myocardium secondary to coronary artery disease. "Despite its established value, only the BACEF score systematically incorporates albumin among contemporary acute coronary syndrome (ACS) risk stratification tools." (PMID 41377920, 2025). "Low albumin independently has been linked to worse outcomes following acute coronary syndrome and with increased likelihood of complications." (PMID 38152782, 2023). "The diagnostic usefulness of ischemia-modified albumin in acute coronary syndrome (ACS) has been questioned." (PMID 35630031, 2022). "Patients with acute coronary syndrome with albumin <3.5 g/dl had a 2.80-fold higher risk of death compared to those with albumin ≥3.5 g/dl [OR (95% CI), 2.80 (1.11 1–7.00)]." (PMID 36523355, 2022). "Low albumin levels are also thought to be an independent predictor of thrombotic burden in people with acute coronary syndrome." (PMID 40510491, 2025). "The albumin cobalt binding test, which detects structural changes in the N-terminus of albumin, shows a sensitivity of 70%, specificity of 80%, and a positive predictive value of 96% for acute coronary syndrome." (PMID 40244022, 2025). "In patients with acute coronary syndrome, the serum albumin levels are significantly lower in those with CI-AKI than in those without CI-AKI, and the serum albumin level is an independent predictor of CI-AKI." (PMID 38773489, 2024). "In the late 1990s, researchers discovered that patients with acute coronary syndrome had lower levels of exogenous cobalt (Co+2) binding to human serum albumin." (PMID 39336570, 2024). "The U.S. Food and Drug Administration (FDA) has approved ischemia-modified albumin (IMA) as a serum biomarker for cardiac ischemia, which is used in the risk assessment of patients suspected of having acute coronary syndrome." (PMID 39336570, 2024). "Limited studies have been conducted worldwide in evaluating the role of uric acid to albumin ratio (UAR) in predicting severity or poor outcomes in acute coronary syndrome (ACS) patients." (PMID 38152782, 2023). "In this study, we investigated the relationship between long-term mortality and the CRP/albumin ratio in patients with acute coronary syndromes (ACS)." (PMID 38022331, 2023). "Accumulating evidence has shown that low albumin level is a well-established risk factor for its subtypes, such as stable CHD, acute coronary syndrome, acute and chronic HF, and ischemic stroke." (PMID 36523355, 2022). "Low serum albumin level was an independent predictor of in-hospital mortality in patients with acute coronary syndrome (ACS)." (PMID 35300600, 2022). "Several clinical studies have shown that low albumin level is anindependent predictor of prognosis in patients with acute coronary syndromes." (PMID 39077142, 2022). "Acute coronary syndrome is an inflammatory state, and the serum albumin level often decreases in this situation." (PMID 36341223, 2021). "A cross-sectional study demonstrated that serum albumin ≤35 g/L independently predicted HDL-C<30 mg/dL in patients with acute coronary syndrome." (PMID 34717644, 2021). "A growing set of clinical evidence suggests that neutrophil-to-lymphocyte ratio (NLR), CRP, albumin, and lymphocyte are easily accessible and cheap markers to assess inflammation, especially in acute coronary syndromes." (PMID 33094574, 2020). "The prognostic utility of serum albumin level as a predictor of survival in patients with acute coronary syndrome (ACS) has attracted considerable attention." (PMID 31815281, 2020). "In another study on subjects with acute coronary syndrome undergoing percutaneous coronary intervention, higher CRP and lower serum albumin levels were significantly associated with contrast-induced nephropathy in univariate analyses." (PMID 31889082, 2019).
acute coronary syndrome (continued). "We conclude that a conceptual change from “N-terminal modified” to “FA-occupied” albumin is required to better delineate IMA in patients with acute coronary syndrome." (PMID 28356609, 2017). "This work sought to determine whether the Pan-Immune-Inflammatory Value (PIV) and the Hemoglobin-Albumin-Lymphocyte-Platelet (HALP) score could serve as independent prognostic indicators in individuals presenting with acute coronary syndrome." (PMID 41753347, 2026). "In addition, one recent study found that a high-sensitivity C-reactive protein (CRP) to the albumin ratio was independently correlated with short-term major adverse cardiac events including CS in patients with acute coronary syndrome (ACS)." (PMID 33294452, 2020). "Thus, the new nomenclature may be useful in differentiating albumin modification occurring in acute coronary syndrome with myocardial ischemia from chronic disease with increased oxidative stress." (PMID 28356609, 2017). "CRP, albumin, and NLR have been proposed as potential biomarkers for inflammation, particularly in the context of acute coronary syndromes." (PMID 40506944, 2025). "Elevated SII has been associated with poor prognosis in cardiovascular disease, acute coronary syndromes in CKD, urinary albumin excretion, and mortality in patients with SARS-CoV-2 infection and CKD." (PMID 41149629, 2025). "As compared to non‐acute coronary syndromes (ACS) patients, ACS patients have lower BMI, sodium, albumin (ALB), and higher RBC, WBC, BPC, neutrophil (%), NT‐proBNP, hs‐cTnI, myoglobin, CK‐MB, TB, LDL‐C, AST, and CK." (PMID 37323876, 2023). "In line with what has been suggested recently in the literature, we conclude that a shift from the concept of “N-terminal modified” to “FA-occupied” albumin is required, as this better describes IMA in patients with acute coronary syndrome." (PMID 28356609, 2017). "Although the albumin cobalt binding test was accepted as a potentially powerful marker for discriminating acute coronary syndrome from nonischemic chest pain, its usefulness has been brought into question in recent years." (PMID 28356609, 2017). "Furthermore, if we assume that IMA is “FA-occupied” albumin rather than “N-terminal modified” albumin in patients with acute myocardial ischemia, then we conclude that IMA measured via an ELISA assay is useless for discriminating acute coronary syndrome from nonischemic chest pain." (PMID 28356609, 2017).
Hyperbilirubinemia (68 papers, 2008 to 2026). An increased amount of bilirubin in the blood. "The bilirubin/albumin molar ratio is high in infants with hyperbilirubinemia, which increases their susceptibility to the administration of competing drugs." (PMID 37371159, 2023). "The aim of this study is to determine the value of the questions asked in routine follow-up, the cord blood bilirubin (CBB) and bilirubin/albumin (B/A) ratio in estimating the risk of developing hyperbilirubinemia." (PMID 37476881, 2023). "Overall, our study suggests that measuring cord serum bilirubin, albumin, reticulocyte, and nucleated red blood cell levels can help predict the risk of hyperbilirubinemia in neonates." (PMID 37197121, 2023). "When hyperbilirubinemia turned to acute liver failure, a large amount of endotoxin, cytokines and other pathogenic factors, especially those associated with albumin, accumulated in plasma." (PMID 34425880, 2021). "Those with a TSB above 250 μmol/L were investigated to determine the cause of hyperbilirubinemia and were randomized to either phototherapy and 20% albumin or phototherapy and saline." (PMID 31547861, 2019). "Accordingly albumin infusion has been proposed to reduce the risk of kernicterus in acute phases of hyperbilirubinemia and in hyperbilirubinemic neonates requiring exchange transfusion, but the efficacy of the treatment is controversial." (PMID 28036021, 2016). "The results indicate that a cord bilirubin level ≥1.75 mg/dL, a cord albumin level below 3.75 g/dL, a cord reticulocyte level of 4.95%, and a cord nRBC level of ≥3.5% can serve as useful predictive tools for identifying neonates at risk of developing hyperbilirubinemia after 72 hours of life." (PMID 37197121, 2023). "However, previous studies also reported that total bilirubin or the ratio of total bilirubin to albumin could predict the level of free bilirubin and the neurological dysfunction caused by hyperbilirubinemia." (PMID 34572977, 2021). "Our findings confirm that intravenous albumin infusion before exchange transfusion is an effective treatment for neonatal hyperbilirubinemia, contributing to both bilirubin reduction and shortened phototherapy duration." (PMID 40735252, 2025). "This meta‐analysis demonstrates that administering albumin before exchange transfusion significantly reduces total serum bilirubin levels and the duration of phototherapy in neonates with hyperbilirubinemia." (PMID 40735252, 2025). "This meta‐analysis evaluated the effectiveness of albumin infusion before blood exchange in managing neonatal hyperbilirubinemia." (PMID 40735252, 2025). "The present meta‐analysis is the first meta‐analysis in the world that has been comprehensively conducted to determine the effect of intravenous albumin administration before exchange transfusion in infants with hyperbilirubinemia." (PMID 40735252, 2025). "This meta‐analysis aimed to assess the impact of intravenous albumin administration before exchange transfusion in infants diagnosed with hyperbilirubinemia." (PMID 40735252, 2025). "The effect of albumin administration on the total bilirubin in neonatal with hyperbilirubinemia based on type of administrations and neonatal weight." (PMID 40735252, 2025). "This meta‐analysis aims to systematically evaluate the effect of intravenous albumin administration before exchange transfusion on bilirubin levels and treatment outcomes in infants with hyperbilirubinemia." (PMID 40735252, 2025). "Generally, the detection of TSB, free bilirubin, albumin levels, B/A ratio, and albumin–bilirubin binding have been proposed for neonates with hyperbilirubinemia, with individual or combined uncertain predictive utility." (PMID 37371159, 2023). "Cord blood albumin of ≥3.75 g/dl was seen in 93 neonates, of which 18 (19.4%) developed hyperbilirubinemia after 72 hours of life and 15 (50%) with <3.75 g/dl developed hyperbilirubinemia after 72 hours of life." (PMID 37197121, 2023).